NR2C1 (nuclear receptor subfamily 2 group C member 1)
Description:
Orphan nuclear receptor. Binds the IR7 element in the promoter of its own gene in an autoregulatory negative feedback mechanism. Primarily repressor of a broad range of genes. Binds to hormone response elements (HREs) consisting of two 5'-AGGTCA-3' half site direct repeat consensus sequences. Together with NR2C2, forms the core of the DRED (direct repeat erythroid-definitive) complex that represses embryonic and fetal globin transcription. Also activator of OCT4 gene expression. May be involved in stem cell proliferation and differentiation. Mediator of retinoic acid-regulated preadipocyte proliferation.
Synonyms: TR2; TR2-11
Tractability: Small molecule: it belongs to a druggable protein family. PROTAC: UniProt records ubiquitination sites on it; ubiquitination databases record sites on it.
Target class: Nuclear hormone receptor subfamily 2; Transcription factor; Nuclear receptor; Nuclear hormone receptor subfamily 2 group C member 1; Nuclear hormone receptor subfamily 2 group C
Gene: Protein-coding gene on chromosome 12 (95,020,229 to 95,073,628, reverse strand). Ensembl gene ENSG00000120798.
Subcellular location: Nucleus; Nucleus, PML body
Subcellular location (Human Protein Atlas): Nucleoplasm; Cell Junctions; Cytosol
Pathways (Reactome):
Gene expression (Transcription): Nuclear Receptor transcription pathway
Metabolism of proteins: SUMOylation of intracellular receptors
Gene Ontology:
Molecular function: protein binding; sequence-specific double-stranded DNA binding; DNA binding; DNA-binding transcription factor activity, RNA polymerase II-specific; nuclear receptor activity; nuclear steroid receptor activity; RNA polymerase II cis-regulatory region sequence-specific DNA binding; signaling receptor activity; DNA-binding transcription factor activity; DNA-binding transcription repressor activity, RNA polymerase II-specific; histone deacetylase binding; protein homodimerization activity; sequence-specific DNA binding; zinc ion binding
Biological process: negative regulation of transcription by RNA polymerase II; cell differentiation; regulation of transcription by RNA polymerase II; intracellular receptor signaling pathway; negative regulation of DNA-templated transcription; nuclear receptor-mediated steroid hormone signaling pathway; positive regulation of retinoic acid receptor signaling pathway; regulation of DNA-templated transcription
Cellular component: nucleoplasm; chromatin; nucleus; PML body
Genetic constraint (gnomAD): Loss-of-function variants: 25 observed, 49.82 expected, observed/expected ratio (o/e) 0.5, 90% interval 0.37 to 0.7. The upper end of that interval is the gene's LOEUF score, 0.7, which puts it in group 2 of 6, group 1 being the genes least tolerant of losing a copy. Missense variants: 484 observed, 596.91 expected, observed/expected ratio (o/e) 0.81, 90% interval 0.75 to 0.87. Synonymous variants: 200 observed, 208.81 expected, observed/expected ratio (o/e) 0.96, 90% interval 0.85 to 1.08.
Homologues: Orthologues: macaque NR2C1 (99% identical), chimpanzee NR2C1 (99% identical), dog NR2C1 (96% identical), pig NR2C1 (95% identical), rabbit NR2C1 (95% identical), mouse Nr2c1 (88% identical), guinea pig NR2C1 (87% identical), rat Nr2c1 (84% identical), tropical clawed frog nr2c1 (74% identical), zebrafish nr2c1 (60% identical), Caenorhabditis elegans nhr-41 (23% identical), Drosophila melanogaster Hr78 (20% identical), and 25 more. Paralogues in human: NR2C2 (62% identical), NR2F1 (24% identical), RXRB (24% identical), NR2F2 (23% identical), RXRA (23% identical), RXRG (22% identical), NR2F6 (22% identical), NR2E3 (21% identical), NR2E1 (20% identical), HNF4G (20% identical), HNF4A (18% identical).
Diseases named in the same sentence as NR2C1 in open-access papers:
NR2C1 is named in the same sentence as 12 diseases in open-access papers, as found by Europe PMC text mining. Sharing a sentence is not in itself a finding about the gene and the disease. The quoted sentences say what the papers report.
breast carcinoma (3 papers, 2015 to 2018). "In ER+/breast-cancer cells, NR2C1 suppresses ERα-mediated transcriptional activity, blocking ERα-binding to DNA via formation of an ERα-NR2C1 heterodimer." (PMID 26894976, 2016). "NR2C1 may indirectly contribute to ATRA anti-estrogenic activity in ER+/breast-cancer, as the retinoid controls the activity of this NR in other cellular contexts." (PMID 26894976, 2016). "NR2C1 suppresses androgen-mediated AR transactivation, which may be of therapeutic interest in AR+/mammary-tumors." (PMID 26894976, 2016). "Similarly to REV-ERB isoforms, TR2 (NR2C1) is a transcriptional repressor, and inhibits ERα-mediated transcription to regulate cell proliferation in breast cancer cells." (PMID 26300846, 2015). "NR2C1 and NR2C2 levels are lower in breast-cancer than normal tissue." (PMID 26894976, 2016). "The nuclear receptor subfamily members NR2C1 and NR2C2 were found to be down-regulated in breast cancer but were not proposed as prognostic markers for any cancer." (PMID 30020984, 2018). "The few available data do not provide clues as to the relevance of NR2C1 and NR2C2 in breast-cancer, but it can be suggested that the two receptors are anti-oncogenic." (PMID 26894976, 2016).
endometriosis (2 papers, 2017 to 2019). The growth of functional endometrial tissue in anatomic sites outside the uterine body. "Five mSNPs associated with DNAm probe sites closest to GREB1, C11orf46, NR2C1, KDR and WNT4 are located within regions associated with endometriosis risk." (PMID 30871624, 2019). "Of these eight loci, three were associated with all endometriosis (LAMC3, CAPN14 and DEFA1), and six with Stage B disease (NAALADL2, NR2C1, C14orf132, FOXP2, CDH20 and LAMC3)." (PMID 28333195, 2017).
glioma (2 papers, 2022 to 2026). A benign or malignant brain and spinal cord tumor that arises from glial cells (astrocytes, oligodendrocytes, ependymal cells). "From these genes, 8 were identified as independent prognostic factors for glioma (FGFR1, FLT3, VTN, NR2C1, SEMA4G, CFP, S100P, CHGB)." (PMID 41596318, 2026). "Furthermore, the roles of the IGRPS genes NR2C1, SEMA4G, CFP, and CHGB in gliomas and other cancers are uncharacterized." (PMID 41596318, 2026). "The role of other genes (NR2C1, SEMA4G, CFP, CHGB) included in IGRPS has not been elucidated in gliomas and other tumors." (PMID 36676646, 2022).
pancreatic cancer (2 papers, 2011 to 2024). "In turn, the most commonly deleted gene was MYOCD, a cancer related gene which also displayed LOH in most of our cases (80%); other frequently deleted cancer-associated genes included the EYA3, NR2C1, PTAFR, and the DCC cancer associated genes which have also been involved in pancreatic cancer." (PMID 21811587, 2011). "The enhancer targeting miR-492 activates NR2C1 expression and further enhances EMT in pancreatic cancer via the TGF-β/Smad3 pathway." (PMID 38943031, 2024).
allergic rhinitis (1 paper, 2012). Inflammation of the nasal mucous membranes caused by an IgE-mediated response to external allergens. "It has recently been reported that NR2C1 increased in nasal mucosal from patients with allergic rhinitis." (PMID 22701743, 2012).
cervical cancer (1 paper, 2018). A primary or metastatic malignant neoplasm involving the cervix. "Consequently, to our knowledge the functional association of receptors including CCR6, EPHB2, NR2C1, and NR2C2 with cervical cancer is being proposed for the first time in this study." (PMID 30020984, 2018).
tumor (1 paper, 2014). "There was, however, significant correlation of four genes with tumor size, where one gene, NR2C1 (nuclear receptor subfamily 2, group C, member 1), showed a positive correlation that is increased expression with larger tumor." (PMID 25325012, 2014). "There were four genes with a significant p-value, and only one of them, the NR2C1 was positively correlated with tumor size." (PMID 25325012, 2014).
NR2C1 also shares sentences with these, for which no sentence is quoted: cancer (3 papers); adrenal hypoplasia congenita (1); colon cancer (1); thyroid cancer (1); type 2 diabetes (1).